NISCH (nischarin)
Description:
Acts either as the functional imidazoline-1 receptor (I1R) candidate or as a membrane-associated mediator of the I1R signaling. Binds numerous imidazoline ligands that induces initiation of cell-signaling cascades triggering to cell survival, growth and migration. Its activation by the agonist rilmenidine induces an increase in phosphorylation of mitogen-activated protein kinases MAPK1 and MAPK3 in rostral ventrolateral medulla (RVLM) neurons that exhibited rilmenidine-evoked hypotension (By similarity). Blocking its activation with efaroxan abolished rilmenidine-induced mitogen-activated protein kinase phosphorylation in RVLM neurons (By similarity). Acts as a modulator of Rac-regulated signal transduction pathways (By similarity). Suppresses Rac1-stimulated cell migration by interacting with PAK1 and inhibiting its kinase activity (By similarity). Also blocks Pak-independent Rac signaling by interacting with RAC1 and inhibiting Rac1-stimulated NF-kB response element and cyclin D1 promoter activation (By similarity). Also inhibits LIMK1 kinase activity by reducing LIMK1 'Tyr-508' phosphorylation (By similarity). Inhibits Rac-induced cell migration and invasion in breast and colon epithelial cells (By similarity). Inhibits lamellipodia formation, when overexpressed (By similarity). Plays a role in protection against apoptosis. Involved in association with IRS4 in the enhancement of insulin activation of MAPK1 and MAPK3. When overexpressed, induces a redistribution of cell surface ITGA5 integrin to intracellular endosomal structures.
Synonyms: I-1; IR1; hIRAS; IRAS; KIAA0975
Tractability: Small molecule: an approved drug acts on it; a structure with a bound ligand is known; a high-quality ligand is known; it belongs to a druggable protein family. Antibody: its Gene Ontology location is reachable by antibodies, with high confidence; UniProt places it where antibodies can reach, with medium confidence. PROTAC: ubiquitination databases record sites on it; its protein half-life has been measured; a small molecule that binds it is known.
Target class: Other cytosolic protein
Gene: Protein-coding gene on chromosome 3 (52,455,118 to 52,493,068, forward strand). Ensembl gene ENSG00000010322.
Subcellular location: Cell membrane; Cytoplasm; Early endosome; Recycling endosome
Subcellular location (Human Protein Atlas): Cytosol; Nucleoplasm; Cytokinetic bridge; Microtubules; Vesicles
Pathways (Reactome):
Signal Transduction: RAC1 GTPase cycle; RND2 GTPase cycle; RND3 GTPase cycle
Gene Ontology:
Molecular function: identical protein binding; protein binding; integrin binding; phosphatidylinositol binding
Biological process: Rac protein signal transduction
Cellular component: cytosol; membrane; plasma membrane; cytoplasm; early endosome; recycling endosome
Genetic constraint (gnomAD): Loss-of-function variants: 52 observed, 134.24 expected, observed/expected ratio (o/e) 0.39, 90% interval 0.31 to 0.49. The upper end of that interval is the gene's LOEUF score, 0.49, which puts it in group 2 of 6, group 1 being the genes least tolerant of losing a copy. Missense variants: 1,627 observed, 2,035.8 expected, observed/expected ratio (o/e) 0.8, 90% interval 0.77 to 0.83. Synonymous variants: 854 observed, 886.01 expected, observed/expected ratio (o/e) 0.96, 90% interval 0.91 to 1.02.
Homologues: Orthologues: chimpanzee NISCH (99% identical), macaque NISCH (96% identical), pig NISCH (92% identical), guinea pig NISCH (90% identical), mouse Nisch (89% identical), rat Nisch (89% identical), rabbit NISCH (88% identical), dog NISCH (80% identical), tropical clawed frog nisch (46% identical), zebrafish nisch (46% identical), Caenorhabditis elegans nish-1 (12% identical), Drosophila melanogaster CG11807 (12% identical). Paralogues in human: STK11IP (15% identical).
Diseases named in the same sentence as NISCH in open-access papers:
NISCH is named in the same sentence as 62 diseases in open-access papers, as found by Europe PMC text mining. Sharing a sentence is not in itself a finding about the gene and the disease. The quoted sentences say what the papers report.
breast cancer (20 papers, 2013 to 2025). A primary or metastatic malignant neoplasm involving the breast. "Loss of NISCH expression was previously reported as a consequence of a loss of heterozygosity and microdeletions of the NISCH gene in breast cancer and NISCH promoter hyper-methylation in ovarian cancer." (PMID 38781180, 2024). "Analysis of a total of 962 patients with breast cancer revealed that 0.3% of invasive carcinomas showed loss of Nischarin expression and that 0.7% of invasive carcinomas expressed mutated Nischarin." (PMID 39070120, 2023). "Once miR-27b was up-regulated in breast cancer, it would cause the down-regulation of Nischarin and the activation of the NFκB signaling pathway." (PMID 35281863, 2022). "Once miR-27b is up-regulated in breast cancer, it causes down-regulation of Nischarin and activation of the NFκB signal pathway, followed by further increase in miR-27b transcription." (PMID 31763673, 2019). "Nischarin has also recently been shown to directly associate with tumor suppressor LKB1 in breast cancer cells." (PMID 25695373, 2015). "The expression levels of Nischarin were previously demonstrated to be significantly higher in normal breast tissue compared with breast cancer tissue, and the loss of Nischarin expression in breast cancer tissue is hypothesized to be due to a loss of heterozygosity." (PMID 25695373, 2015). "Our data reports a new redox player in cell migration and invasion, while supporting the potential application of NISCH-derived protein-based therapeutics for breast cancer." (PMID 41213437, 2025). "Bearing in mind that most findings about NISCH role in cancer stemmed from the breast cancer research and that most of the examined patient data were from females, we aimed to perform a multidimensional pan-cancer analysis of nischarin in both sexes." (PMID 38781180, 2024). "In HNSC, it was reported that miR-2355-5p decreased NISCH expression, leading to higher tumor cell proliferation, and knockdown of miR-23b and miR-27b was reported to upregulate nischarin and repress breast cancer growth." (PMID 38781180, 2024). "Nischarin was reported to be a tumor suppressor that plays a critical role in breast cancer initiation and progression, and a positive prognostic marker in breast, ovarian and lung cancers." (PMID 38781180, 2024). "Seminal work on elucidating NISCH role in breast cancer initiation and progression has been done by the Alahari group." (PMID 38781180, 2024). "NISCH is ubiquitously expressed in the mammary gland and frequently expressed at low levels in breast cancers." (PMID 39303918, 2024). "In breast cancer cells, miR-23b-3p negatively regulates Nischarin, an intracellular protein that acts as a tumor suppressor by regulating the metastatic behavior of tumor cells." (PMID 31097683, 2019). "Understanding the role Nischarin and other tumor suppressors play in the prevention of breast cancer cell survival and migration will provide more knowledge for novel breast cancer therapies." (PMID 29415725, 2018). "In the present study, we investigate the role of Malat1 in breast cancer in the expression background of the gene Nischarin, a protein previously characterized by our lab." (PMID 29912916, 2018). "These experiments demonstrate an important role of Nischarin in regulating cell attachment, which adds to our understanding of the early events of the metastatic process in breast cancer." (PMID 29415725, 2018). "Taken together, our findings suggest that the presence of Nischarin in breast cancer cells leads to a down regulation of MMPs 1, 2, and 9, which leads to a reduction in ECM degradation." (PMID 29415725, 2018). "Our initial screens of breast cancer MDA-MB-231 cells showed that Malat1 expression was positively correlated with the level of Nischarin present in the cell." (PMID 29912916, 2018). "Nischarin is a well characterized tumor suppressor protein and actively represses cell proliferation, migration, and invasion in breast cancer." (PMID 29912916, 2018).
breast cancer (continued). "Nischarin is a cytoplasmic protein expressed in various organs that plays an inhibitory role in cell migration and invasion and the carcinogenesis of breast cancer cells." (PMID 26670864, 2015). "Further studies are required to verify the role of Nischarin as a prognostic marker for breast cancer metastasis." (PMID 25695373, 2015). "The expression of miR23b and miR27b, which are highly expressed in breast cancer cells, was shown to be inversely correlated with Nischarin expression levels." (PMID 25695373, 2015). "In the present study ELISA analysis revealed significantly lower expression levels of Nischarin in breast cancer tissues compared with adjacent normal tissues in patients with PBC." (PMID 25695373, 2015). "The correlation between Nischarin expression levels and breast cancer metastasis was also examined, in order to aid the elucidation of the role of Nischarin in the occurrence, development and metastasis of PBC." (PMID 25695373, 2015). "The present study aimed to investigate the expression of Nischarin protein in primary breast cancer (PBC), and to evaluate its role in tumor metastasis." (PMID 25695373, 2015). "In conclusion, the results of the present study revealed that Nischarin expression was significantly lower in breast cancer tissues compared with adjacent normal tissues in Chinese patients with PBC." (PMID 25695373, 2015). "Overexpression of Nischarin in MCF-7 breast cancer cells also resulted in the inhibition of cell migration, as indicated by a Transwell assay, although Nischarin overexpression did not significantly influence cell adhesion." (PMID 25695373, 2015). "NISCH has been established recently as a tumour suppressor in breast cancer and has significantly higher expression in normal breast tissue samples compared to tumour samples." (PMID 25488803, 2014). "Nischarin is a protein known to inhibit breast cancer cell motility by regulating the signaling of the Rho GTPase family." (PMID 23342172, 2013). "However, RAB14 actively interacts with Nischarin by regulating the production of exosomes in breast cancer cells, subsequently affecting tumor cell adhesion, cell migration, tumor growth, and metastasis." (PMID 39376611, 2024). "It was reported that exogenous expression of NISCH could suppress breast cancer cell survival and motility in vitro and growth in vivo." (PMID 38781180, 2024). "In addition to the dominantly cytoplasmic and membranous localization that was reported in healthy and breast cancer cells, our group reported that NISCH was also present in the cell nucleus in melanoma tissues." (PMID 38781180, 2024). "Therefore, Nischarin positive breast cancer cells have a limited ability to degrade the ECM because they have decreased expression of MMPs." (PMID 29415725, 2018). "However, the work we present here supports the notion that it functions as a contextual tumor suppressor gene, specifically, in breast cancers expressing sufficient levels of Nischarin." (PMID 29912916, 2018). "Nischarin is a tumor suppressor which is frequently underexpressed in breast cancer." (PMID 29912916, 2018). "However, to the best of our knowledge, the role of Nischarin in breast cancer metastasis has previously only been studied in vitro and the mechanisms underlying Nischarin-mediated inhibition of metastasis remain to be elucidated." (PMID 25695373, 2015). "We demonstrated that epithelial breast cancer cell lines, MCF7 and MDA-MB-231, expressing NISCH wild-type (WT), compared to its cysteine mutant (C185S), exhibit increased migration and invasion in response to oxidative stress, such as limited glucose." (PMID 41213437, 2025). "In contrast to the findings that exogenous expression of NISCH in breast cancer cells suppresses cell survival, in vitro studies from the early 2000s on the function of IRAS (then considered a human homologue of mouse nischarin) support the opposite claim." (PMID 38781180, 2024).
breast cancer (continued). "The proteins determined by SDS–PAGE to be expressed in mammary tissues in the rat model of DMBA-induced mammary cancer were thought to be HER-2, Nischarin, COX-2, Albumine, Vimentin, Actin, TNF-α, p16, and FABP3." (PMID 39070120, 2023). "Knockdown of miR-27b augmented Nischarin (NISCH) and suppressor of tumorigenicity 14 (ST14) expression in human breast cancer, down-regulated STAT3, c-myc and cyclin D1 in glioma." (PMID 26910911, 2016). "NISCH was previously reported to be a positive prognostic marker in breast cancer, but in our examination of the TCGA dataset, it was not statistically significant." (PMID 38781180, 2024). "In the present study, the expression levels of Nischarin in breast cancer tissues were compared with those in adjacent noncancerous tissues." (PMID 25695373, 2015). "The significant differences in the expression of Nischarin between: i) Cancer tissue and noncancerous tissue and ii) patients with and without lymph node metastasis, suggested that Nischarin may have a significant role in tumor occurrence and metastasis of breast cancer." (PMID 25695373, 2015).
ovarian carcinoma (4 papers, 2020 to 2024). A malignant neoplasm originating from the surface ovarian epithelium. "Cancer-specific methylation of the NISCH gene was found in the breast, ovarian, lung, head and neck, and gastric cancers and NISCH loss of heterozygosity was reported in breast and ovarian cancer." (PMID 38781180, 2024). "NISCH was found to be downregulated in breast and ovarian cancer tissues compared to the healthy counterparts and was found to be a marker of better prognosis." (PMID 38781180, 2024). "However, in ovarian cancer, the decreased expression of NISCH can make cancer cells deteriorate rapidly including proliferation and metastasis." (PMID 33046974, 2020). "Ovarian cancer data set only had information for a single NISCH promoter probe as opposed to 10 probes for the other analyzed cancer types and was excluded from further analysis." (PMID 38781180, 2024).
diabetes mellitus type II (3 papers, 2013 to 2025). "Only seven genes had the same direction of effect for comparison of type 2 diabetes samples and healthy samples in all eight datasets: LOC112268118 and MPO had positive logFC, and IL18BP, DELE1, TSPAN32, ITFG2, and NISCH all had negative logFC." (PMID 41465472, 2025).
lung carcinoma (3 papers, 2021 to 2025). "Nischarin was so far known as a novel tumor suppressor gene whose downregulation promotes tumorigenesis, tumor progression, and poor survival in breast, ovarian and lung cancer patients." (PMID 38781180, 2024). "The tumor and disease suppressor role of NISCH has also been identified in lung cancer." (PMID 34727954, 2021).
schizophrenia (3 papers, 2021 to 2023). A major psychotic disorder characterized by abnormalities in the perception or expression of reality. "In line with our results, another recent study also demonstrated that NISCH was a risk gene shared between schizophrenia and BD through integrative analyses of GWAS and life course consistent methylation quantitative trait loci (meQTLs) datasets." (PMID 37443018, 2023). "Since the presence of Alu element at rs71052682 was linked with the psychiatric risk T-allele at rs2251219, it is reasonable to hypothesize that higher mRNA expression of NISCH is associated with an increased risk of schizophrenia and BD." (PMID 37443018, 2023). "The genomic region of chromosome 3p21.1 contained several genes pleiotropically associated with both SA and schizophrenia, including PBRM1, NEK4, GNL3, ITIH4 and NISCH." (PMID 38016951, 2023).
glioma (2 papers, 2016 to 2024). A benign or malignant brain and spinal cord tumor that arises from glial cells (astrocytes, oligodendrocytes, ependymal cells). "Interestingly, the rest of the tumor types also had nuclear localization of NISCH, ranging from 10% of samples (glioma) to 50% of the stained samples (COAD, HNSC, LIHC, PAAD)." (PMID 38781180, 2024).
renal carcinoma (2 papers, 2021 to 2024). A carcinoma arising from the epithelium of the renal parenchyma or the renal pelvis. "Sex-related difference in NISCH expression was detected in two renal cancer subtypes–KIRC and KIRP –with higher NISCH levels in tumor samples obtained from females, while for other cancers expression in tissues from female and male patients were similar." (PMID 38781180, 2024). "The α and β breakpoints fall within exons of the NISCH gene while the γ breakpoint falls within exon 27 of PBRM1, a gene previously shown to be a cancer driver in renal carcinoma and intrahepatic cholangiocarcinomas." (PMID 33823910, 2021). "In renal cancer more than 50% of samples did not express NISCH at all." (PMID 38781180, 2024).
brain cancer (1 paper, 2013). A primary or metastatic malignant neoplasm affecting the brain. "As we found that Nischarin is a key regulatory molecule that controls neuronal migration, it may have important physiological and pathophysiological implications for brain development, dementia, brain cancers and neurodegenerative disorders." (PMID 23342172, 2013).
colorectal carcinoma (1 paper, 2024). A malignant epithelial neoplasm that arises from the colon or rectum and invades through the muscularis mucosa into the submucosa. "We were surprised that NISCH expression was an unfavorable prognostic marker in colorectal carcinoma, as most of the CRC are adenocarcinomas." (PMID 38781180, 2024).
endometrial cancer (1 paper, 2024). Primary or metastatic malignant neoplasm involving the endometrium (mucous membrane that lines the endometrial cavity). "Therefore, we examined the subcellular distribution of NISCH across tumors in the Human Protein Atlas and found that only in breast and endometrial cancer NISCH localization was restricted to the cytoplasmic and membranous." (PMID 38781180, 2024).
glioblastoma (1 paper, 2024). The most malignant astrocytic tumor (WHO grade IV). "We further looked at the common pathways associated with NISCH by sex in the Reactome gene sets in melanoma and glioblastoma, as these two cancer types share the embryonic origin." (PMID 38781180, 2024). "Prompted by our previous study on melanoma, we set out to examine possible sex-related differences in NISCH prognostic role but have only found differences in survival by sex in two other cancer types: glioblastoma and thyroid cancer." (PMID 38781180, 2024).
kidney cancer (1 paper, 2024). Primary or metastatic malignant neoplasm involving the kidney. "Our results complement previous findings that NISCH promoter methylation is frequent in lung and kidney cancer and can affect NISCH expression." (PMID 38781180, 2024).
lymph node metastasis (1 paper, 2015). "The mean concentration of Nischarin protein was found to be significantly lower in tissues from patients with lymph node metastasis compared with those of patients without lymph node metastasis (4.69±2.40 vs. 7.04±3.47 ng/ml; P=0.004)." (PMID 25695373, 2015). "Furthermore, cancer tissue from patients with lymph node metastasis had significantly lower levels of Nischarin protein (4.69±2.40 ng/ml) than those of patients without lymph node metastasis (7.04±3.47 ng/ml; P=0.004)." (PMID 25695373, 2015).
melanoma (1 paper, 2024). A malignant, usually aggressive tumor composed of atypical, neoplastic melanocytes. "In the gene set enrichment analysis NISCH associated with both overlapping and distinct signaling pathways in female and male melanoma patients." (PMID 38781180, 2024). "As we previously reported, NISCH had the opposite prognostic value for female and male melanoma patients." (PMID 38781180, 2024). "We have previously reported the nuclear localization of NISCH in melanoma." (PMID 38781180, 2024). "Surprisingly, although NISCH expression was downregulated in melanoma tissue compared to the uninvolved skin, our group found that it was a favorable prognostic marker only in female melanoma patients, but not in males." (PMID 38781180, 2024).